CP (ceruloplasmin)
Diseases named in the same sentence as CP in open-access papers (continued):
Sharing a sentence is not in itself a finding about the gene and the disease.
infection (continued). "At 56-days post-infection, two proteins, inter-alpha-trypsin inhibitor heavy chain H3 and ceruloplasmin, were up-regulated: while inter-alpha-trypsin inhibitor heavy chain H3 is related to inflammation and carcinogenesis, ceruloplasmin is a serum glycoprotein related to the acute phase of infection." (PMID 36227939, 2022). "We identified infection or colonization through both clinical manifestations and laboratory examinations (computed tomography examinations) and found 80.88% (110/136) of them were infected and 19.12% (26/136) have CP-Kpn colonization." (PMID 35546482, 2022). "Patient 28 was found to have both a mixed infection and within-host evolution of CP-Kpn." (PMID 35546482, 2022). "Indeed, while the number of infection-related CP-Ec isolates was regularly increasing, their proportion compared to the total number of received and sequenced isolates decreased by twofold, with a clear change observed between 2013 and 2014." (PMID 35014866, 2022). "In addition, the following were observed in cats after infection with T. gondii: malate dehydrogenase, serotransferrin, keratin, phosphoglycerate mutase, elongation factor, ceruloplasmin, gelsolin, crystalline alpha chain and annexin A1." (PMID 34906132, 2021). "Importantly, CD86, which was significantly expressed in CP pDC, was further enhanced in CP-AS indicating that asymptomatic infection with SARS-CoV-2 strongly activates pDC." (PMID 34473805, 2021). "One factor that likely contributes to the higher concentration of copper in these environments is the increased presence of ceruloplasmin, a copper-containing protein, as it is an acute-phase reactant that is upregulated under conditions of infection and inflammation in lungs and serum." (PMID 34468162, 2021). "The higher level of CP transcription in the CLECs of the CoPS vs. the H samples may suggest an increased presence of reactive oxygen species during this type of infection." (PMID 32867772, 2020). "Canine serum ceruloplasmin levels are increased during infection, inflammation, and trauma." (PMID 33297385, 2020). "In the challenged groups, only the group FM/CP had obvious lesions at 1 day post-infection (dpi)." (PMID 30483244, 2018). "In addition to dietary Cu, ceruloplasmin levels vary with factors such as age and sex, and rapidly increase in response to exercise and several inflammatory conditions and infection." (PMID 30513571, 2018). "In addition, it is well known that CP is an acute phase reactant, and CP levels in the blood plasma increase when the immune system responds to infection and inflammation." (PMID 29324775, 2018). "Why could CP-PGN play the role of anti-infection through the TLR2, instead of peptidoglycan of other bacteria?" (PMID 29203871, 2017). "In order to test whether an early-onset infection affects plasma CP and Cu levels alike, both biomarkers were determined from plasma of infected and control neonates." (PMID 28358335, 2017). "In summary, interaction between T. cruzi and host cells prompt the release of MVs from both parasite and host cells and this phenomenon may contribute to evasion of CP and LP complement activation and to increase host cell infection." (PMID 28473804, 2017). "In the localized abdominal MRSA infection, stimulation of CP or CP-PGN could prevent local infection from progressing to systemic infection, with improved survival rate, reduced bacterial load and alleviated inflammatory damage of lung." (PMID 29203871, 2017). "The diversity of capacity of activating macrophages induced by CP and CP-PGN may result in distinct resistance to MRSA in different infection models." (PMID 29203871, 2017). "These molecules, including termicin, prolixicin, thaumatin-like protein, lysozyme, cathepsin, asparaginyl endopeptidase-like cysteine peptidase (AE-like CP), and metacaspase-like cysteine peptidase (MCA-like CP), are upregulated upon pathogenic infection, and they directly attack pathogens." (PMID 28410430, 2017).
infection (continued). "In order to achieve the better effect, it was suggested that C. pyruviciproducens was good for the local infection, in contrast, CP-PGN could be chosen for systemic blood infection to reduce the systemic injury." (PMID 29203871, 2017). "At a later stage of T. cruzi infection (days post-infection), CP becomes activated when anti-trypomastigote-specific IgM and IgG antibodies are produced allowing C1q binding and the activation of C1r and C1s serine proteases that cleave C4 and C2 forming the CP C3 convertase." (PMID 28473804, 2017). "However, in contrast with BP/HuN/414/10, the replication and infection ability of the isolated CP/XH/420/10 (H7N1) virus in chickens and ducks showed obvious differences." (PMID 27458455, 2016). "This suggests that the ceruloplasmin protein detected late in the infection may have been synthesised by the kidney, rather than being transported from the liver." (PMID 27362522, 2016). "It showed that CP-IDL could inhibit infection of all these resistant strains, which are much more potent than CP or T20." (PMID 27666394, 2016). "Additionally, in vivo protective effect of CP against divergent influenza A subtypes was determined in a BALB/c mouse infection model." (PMID 27484768, 2016). "Ceruloplasmin, an acute-phase protein, has been reported to increase in various acute inflammatory conditions, including injury, malignancy, cardiovascular disease, and infection." (PMID 23505556, 2013). "In addition, secondary bands were seen in the blots of CP and CPΔN, which is consistent with the sizes of astrovirus cleavage products described upon infection in mammalian cells." (PMID 24376619, 2013). "The movement of PepMV-CP mutants could be restored by providing CP in trans but there were only few infection foci, suggesting that PepGFPΔCP was able to initiate infection foci but with a low efficiency." (PMID 21396092, 2011). "Moreover, understanding this association could pave the way for therapeutic research focusing on modulating ceruloplasmin levels to potentially mitigate the severity of the infection." (PMID 39574108, 2024). "Overall, we observed an increase in serum iohexol levels during peak infection, along with significant changes in performance parameters, lesion scores, mRNA abundance of key TJ proteins, pro-inflammatory cytokines, and gut health markers in EM and EM + CP birds compared to NC and CP birds." (PMID 39759108, 2024). "A limitation of the present study may be that different protocol designs were used to collect CP-Kpn strains during the pandemic and pre-pandemic periods; justified by the difficulty in collecting cases of infection/colonization by CP-Kpn during the first phase of the pandemic." (PMID 36671308, 2023). "However, a previous study has shown that a vector carrying GFP under the duplicated PVX SGP and the N-terminal PVX CP, which lacks the first 29 amino acids, is slower to produce systemic infection due to insufficient yield of the CP sgRNA, which cannot provide enough CP for normal infection." (PMID 35632840, 2022). "Among the upregulated genes there are genes that belong to infection-associated inflammatory Acute Phase proteins (APPs), such as Serum amyloid A1 (SSA1, FC = 1599) and A2 (SSA2, FC = 49), colony stimulating factor CSF2 (FC = 1316) and CSF3 (FC = 234), as well as Ceruloplasmin (CP; FC = 46.49)." (PMID 35531332, 2022). "Thus, we hypothesise that fish with lower infection intensities were in an acute phase of the disease, while H GSB restored their ceruloplasmin to control levels later during the progress of infection." (PMID 36088326, 2022). "Moreover, the level of RGNNV CP mRNA expression increased gradually during RGNNV infection." (PMID 33767703, 2021).
infection (continued). "A common hallmark of infection, irrespective of causative microbial agent (e.g., viral, bacterial, fungal), is a marked and progressive increase in serum Cu2+ attributed to CP, suggested to deliver Cu2+ to the sites of infection to attack invading pathogens with Cu2+ toxicity." (PMID 33081049, 2020). "Thus, a higher infection ratio in group CP was expected than in group FM, which was confirmed." (PMID 28595633, 2017). "On the other hand, we found that ceruloplasmin might have a better diagnostic value for aGvHD independent of infection status, as the elevation of ceruloplasmin at onset of aGvHD would be more remarkable than infections." (PMID 23505556, 2013). "Although the diagnostic time points of aGvHD and infections were not all the same, the disparity of ceruloplasmin kinetics between patients only with aGvHD and infection at multi-time points might contribute to explain this question." (PMID 23505556, 2013). "Conclusions: rectal colonization by CP-CRE in hospitalized patients is a serious epidemiological concern, with evidence of clonal spread and subsequent infection in colonized patients." (PMID 41594146, 2026). "Prompt identification of enzyme class in carbapenemase-producing carbapenem-resistant Enterobacterales (CP-CRE) has critical implications for informing appropriate patient treatment, infection prevention, and public health." (PMID 40970712, 2025). "Silencing of CAT1 expression via VIGS led to dramatic reductions in PepMV RNA and CP accumulation, demonstrating that CAT1 acts as a positive regulator of infection." (PMID 41373893, 2025). "Infection by cucumber mosaic virus (CMV) boosts AtTLP1 expression in Nicotiana tabacum and this TLP specifically interacts with the CMV movement protein and CP." (PMID 39532690, 2025). "Several genes such as CP, HP, and ORM1 are involved in the acute-phase response, indicating that a decrease in CEBPB can influence systemic responses to injury, infection, or other stress factors." (PMID 41002959, 2025). "Enhanced infection prevention and control measures should be considered for patients with severe burns of an ABSI score ≥ 10 and those with CP-CRE." (PMID 39881424, 2025). "In two multicentre studies, approximately 8% of CP-GNB infections were community-acquired, with UTIs being the most common infection." (PMID 39766528, 2024). "After infection, we noted heightened TNF-α levels in the respiratory tract of mice pre-treated with Cp 090104 or CP-derived BLPs, while in sera it was markedly lower than in the control group." (PMID 38675794, 2024). "The mice that received the PPV together with live bacteria or the CP-derived BLPs had higher levels of the three cytokines in both BAL and sera compared with the mice that received the PPV alone after the infection with serotype 6B." (PMID 38675794, 2024). "We show that Mn acquisition by MtsABC plays a crucial role in GAS evasion of CP-mediated Mn limitation and contributes to GAS virulence in a mouse model of invasive infection." (PMID 38869295, 2024). "The relative expression levels of NbCRVP and PVY CP in 35S::CRVP-PVY and 35S::00-PVY groups were also detected after PVY-GFP infection of N. benthamiana for 1, 2, 3, and 4 days." (PMID 38191434, 2024). "In this study, we investigated the role of MtsABC in the competition between CP and GAS for Mn during infection and its contribution to GAS pathogenesis." (PMID 38869295, 2024). "Nevertheless, the detection of both phylogroups based on the CP gene supports the notion of multiple GVA strain infections, possibly stemming from distinct infection events." (PMID 38257742, 2023). "The impairment in the broiler growth performance induced by EC infection in the present study was accompanied by an approximately 1.5-fold reduction in the GSH and SOD antioxidants, and a 2-fold increase in the CP and MDA levels." (PMID 36766252, 2023).
infection (continued). "As expected, the T1A/D3G double mutant behaved as controls in term of infection timing and visible symptoms, as well as viral accumulation in upper non-inoculated leaves as estimated by immunodetection of UCBSV CP." (PMID 35180277, 2022). "With the aim of tracking the UCBSV infection in planta, an UCBSV full-length cDNA clone was manipulated to introduce the GFP coding sequence between NIb and CP cistrons." (PMID 35180277, 2022). "The increases in effect sizes of ceruloplasmin, AGP and SAA corresponds to what is expected in the host response to infection as illustrated in dogs, pigs and cattle." (PMID 35902827, 2022). "The yield of CP sgRNA under the heterologous Bamboo mosaic virus (BaMV) SGP was higher and thus the infection rate was comparable to that of the original vector, suggesting that additional sequences to the SGP contribute to efficient sgRNA production." (PMID 35632840, 2022). "The smallest dN/dS ratio (mean 0.070) was that of the CP gene, perhaps because of its many functions: the activation of PVX RNA translation, the transport of infection and viral genome RNA encapsidation." (PMID 33918611, 2021). "Infection with ΔtcpAh mutant A. hydrophila dramatically upregulated CD80/86 expression in fish, and this outcome was attenuated by supplementing CP-TcpAh protein." (PMID 34305858, 2021). "Enterobacteriaceae are a significant contributor to the burden of antibiotic-resistant infections through the production of extended-spectrum beta-lactamases (ESBL-) and carbapenemases (CP-)." (PMID 33930099, 2021). "Early and accurate identification of carbapenemase-producing carbapenem-resistant Enterobacteriaceae (CP-CRE) is extremely important for the treatment and prevention of such infections." (PMID 33434203, 2021). "The strong positive correlations between the transcripts of the CP and SAA3 genes and between those of the CP and HP genes in CLECs imply the combined action of their coded proteins against infection within these cells during chronic mastitis." (PMID 32867772, 2020). "Among the three aptamers, GBN2 showed the strongest capacity to reduce CP mRNA expression, suggesting that this aptamer inhibits RGNNV infection." (PMID 32425897, 2020). "Four days after infection, CRP, HP, and ceruloplasmin were elevated but returned to base-line levels up until 3 weeks after infection." (PMID 31001544, 2019). "For HPX, CP and RBP4 differential abundance was observed only in the FEB stage of the infection, while alterations in their serum abundances during the DEF and CON stages were found to be statistically insignificant (p > 0.05)." (PMID 28667326, 2017). "Collectively, these results indicated that C. pyruviciproducens and CP-PGN promoted differentiation of macrophages into the classic M1 phenotypes, so as to enhance the ability of anti-infection." (PMID 29203871, 2017). "All these results indicated that although CP and CP-PGN improved the same level of survival of mice with abdominal infection, the whole cell of heated CP seemed to be more effective in limiting local infection of MRSA than its PGN." (PMID 29203871, 2017). "The development of transgenic papaya to prevent infection by PRSV has been employed after the successful development of transgenic tobacco, expressing the CP gene of the tobacco mosaic virus, which showed disease resistance." (PMID 24757435, 2014). "CP is an acute-phase plasma protein with ferroxidase activities that is locally produced by activated monocytes/macrophages and retinal glia, and which is abundantly released in the ECM compartment upon response to inflammation, trauma, or infection." (PMID 40650085, 2025). "The ROS generated during the infection triggers the release of antioxidants molecules, including SOD, GPx, catalase, albumin, ceruloplasmin, ferritin, ascorbic acid, α-tocopherol, β-carotene, reduced glutathione, uric acid, and bilirubin, all of which are included in the measurement of TAS." (PMID 39852665, 2025).
infection (continued). "The authors hypothesize that this difference could be due to the silencing suppressors (TGB1 and CP) of the CH2 strain being more efficient than those of the EU strain, thereby allowing CH2 to evade this host defense in single infections." (PMID 41373893, 2025). "Our results confirmed prior reports that minor differences in the inoculum can lead to categorical changes in susceptibility interpretation, particularly impacting the detection of CP-CRE, the isolates that carry the greatest implications for infection control." (PMID 41036946, 2025). "CP, a heterodimer of S100A8 and S100A9 proteins, is recruited to the infection sites as a component of the first line of defenses by infiltrating neutrophils and participates in host defense against several bacterial pathogens, including GAS (5, 9, 11, 19, –, 23)." (PMID 38869295, 2024). "In the case of fluoroquinolones, the evidence is based on infections caused by non-CP-GNB, as data on ciprofloxacin treatment for CP-GNB infections have not been reported." (PMID 39766528, 2024). "CP-CRPA was isolated only from this final serial specimen, suggesting hospital-acquired infection." (PMID 37535466, 2023). "Previous data have suggested that contact precautions, as a component of multimodal infection prevention bundles, have successfully stopped transmission of CP-CRPA though data for non-carbapenemase-producing organisms is lacking." (PMID 36786132, 2023). "Phylogenetic analysis of the 5′ part and the MP/CP region of the GPGV strains showed that the GPGV variants clustered according to the vineyard and not the host, suggesting an on-site infection." (PMID 35890463, 2022). "There has been no need for testing these infants after discharge for CP-CRE as they have not had any signs of sepsis or infection." (PMID 34063374, 2021). "Evaluation of the magnitude of post-infection antibody responses in animals that did not receive CP plasma clearly indicated that IgG dominated the humoral response to all SARS-CoV-2 proteins, with IgG1 being the most dominant subtype." (PMID 33483492, 2021). "TuMV RNAs and CP protein in both IL and systemically infected leaves accumulated less in the NbLHCB3-silenced plants than in non-silenced plants, showing that silencing of NbLHCB3 inhibited TuMV-GFP infection." (PMID 34290685, 2021). "Evaluation of the magnitude of post-infection antibody responses in animals that did not receive CP plasma clearly indicated that IgG dominated the humoral response to all SARS CoV-2 proteins." (PMID 32818217, 2020). "To test this idea we performed a CP stability assay on samples from PVAWT and PVAAG infections." (PMID 33031436, 2020). "Compared with CSE, the overall length of hospitalization and mortality were higher in CP-CRE [median 31 vs 16 days, p<0.0001 and 6/55, 10.9% vs 2/74, 2.7%, p=0.07, respectively], with a global lower rate of infection cure at 60-day follow-up (43/55, 78.2% vs 67/73, 91.8%, p=0.03)." (PMID 30581848, 2018). "In addition, these screening results, in the identification of CP-CRE carriage, can aid in the design of antimicrobial treatment if subsequent infection occurs (or is present already at admission)." (PMID 30111322, 2018). "Anyhow, CP or CP-PGN may be a potential drug alone for cure of mild MRSA infection, and in severe infection, the dosage of antibiotics may be reduced by using a combination of CP or CP-PGN but antibiotics is irreplaceable." (PMID 29203871, 2017). "Therefore, we compared renal ceruloplasmin, CTR1, ATP7A and ATP7B protein levels in animals at different stages of infection." (PMID 27362522, 2016). "This corroborated our observation that hepatic ceruloplasmin levels do not increase during the course of infection." (PMID 27362522, 2016). "With MOI = 0.001, the viral titer of 8PK_BP_CP was increased to a level comparable with WT while with MOI = 0.0001, the viral titer of 8PK_BP_CP relative to 8PK_BP was increased by about 6 and 17-fold at 12 and 24 h post-infection, respectively." (PMID 27272307, 2016).